ZFHX3 (zinc finger homeobox 3)
Description:
Transcriptional regulator which can act as an activator or a repressor. Inhibits the enhancer element of the AFP gene by binding to its AT-rich core sequence. In concert with SMAD-dependent TGF-beta signaling can repress the transcription of AFP via its interaction with SMAD2/3. Regulates the circadian locomotor rhythms via transcriptional activation of neuropeptidergic genes which are essential for intercellular synchrony and rhythm amplitude in the suprachiasmatic nucleus (SCN) of the brain (By similarity). Regulator of myoblasts differentiation through the binding to the AT-rich sequence of MYF6 promoter and promoter repression. Down-regulates the MUC5AC promoter in gastric cancer. In association with RUNX3, up-regulates CDKN1A promoter activity following TGF-beta stimulation. Inhibits estrogen receptor (ESR1) function by selectively competing with coactivator NCOA3 for binding to ESR1 in ESR1-positive breast cancer cells.
Synonyms: ZFH-3; ATBF1; C16orf47; ZNF927; FLJ26184; ATBT; ATFB8; EIG20; SCA4
Tractability: PROTAC: UniProt records ubiquitination sites on it; ubiquitination databases record sites on it.
Gene: Protein-coding gene on chromosome 16 (72,782,885 to 73,891,871, reverse strand). Ensembl gene ENSG00000140836.
Subcellular location: Nucleus; Cytoplasm
Subcellular location (Human Protein Atlas): Nucleoplasm
Pathways (Reactome):
Gene expression (Transcription): RUNX3 regulates CDKN1A transcription
Gene Ontology:
Molecular function: DNA-binding transcription repressor activity, RNA polymerase II-specific; enzyme binding; protein binding; RNA polymerase II cis-regulatory region sequence-specific DNA binding; DNA-binding transcription factor activity; DNA-binding transcription factor activity, RNA polymerase II-specific; DNA binding; nucleic acid binding; zinc ion binding
Biological process: negative regulation of transcription by RNA polymerase II; positive regulation of DNA-templated transcription; response to transforming growth factor beta; circadian regulation of gene expression; positive regulation of cell adhesion; positive regulation of transcription by RNA polymerase II; regulation of DNA-templated transcription; regulation of locomotor rhythm; regulation of transcription by RNA polymerase II
Cellular component: cytoplasm; nuclear body; nucleoplasm; nucleus; transcription regulator complex; chromatin
Genetic constraint (gnomAD): Loss-of-function variants: 42 observed, 287.17 expected, observed/expected ratio (o/e) 0.15, 90% interval 0.11 to 0.19. The upper end of that interval is the gene's LOEUF score, 0.19, which puts it in group 1 of 6, group 1 being the genes least tolerant of losing a copy. Missense variants: 4,981 observed, 4,947.9 expected, observed/expected ratio (o/e) 1.01, 90% interval 0.98 to 1.03. Synonymous variants: 2,293 observed, 2,041.9 expected, observed/expected ratio (o/e) 1.12, 90% interval 1.08 to 1.16.
Cancer hallmarks: suppression of growth (promotes)
Homologues: Orthologues: chimpanzee ZFHX3 (99% identical), macaque ZFHX3 (99% identical), pig ZFHX3 (97% identical), guinea pig ZFHX3 (95% identical), rat Zfhx3 (95% identical), dog ZFHX3 (95% identical), mouse Zfhx3 (95% identical), tropical clawed frog zfhx3 (75% identical), rabbit ZFHX3 (72% identical), zebrafish zfhx3b (67% identical). Paralogues in human: ZFHX4 (54% identical), ZFHX2 (26% identical), LMX1B (3% identical), LHX6 (3% identical), LHX1 (3% identical), LHX5 (3% identical), LHX9 (3% identical), LHX8 (3% identical), LMX1A (3% identical), LHX3 (3% identical), LHX2 (3% identical), LHX4 (3% identical), and 8 more.
Diseases named in the same sentence as ZFHX3 in open-access papers:
ZFHX3 is named in the same sentence as 103 diseases in open-access papers, as found by Europe PMC text mining. Sharing a sentence is not in itself a finding about the gene and the disease. The quoted sentences say what the papers report.
atrial fibrillation (38 papers, 2011 to 2026). A disorder characterized by an electrocardiographic finding of a supraventricular arrhythmia characterized by the replacement of consistent P waves by rapid oscillations or fibrillatory waves that vary in size, shape and timing and are accompanied by an irregular ventricular response. "ZFHX3 (zinc finger homeobox 3) has been associated with stroke, particularly atrial fibrillation (AF), which is a significant risk factor for IS." (PMID 39997650, 2025). "Nonetheless, the ZFHX3 gene acts as a transcription regulator and some of its polymorphisms were associated with risk of atrial fibrillation." (PMID 39060932, 2024). "The transcription factor ZFHX3 is associated with atrial fibrillation, an ageing-related condition, and has a potential role in inflammation." (PMID 37749083, 2023). "ZFHX3 was identified as a crucial risk factor for atrial fibrillation, SYNE2 contributed to cardiac arrhythmia, and GJD3 caused abnormal atrioventricular node conduction." (PMID 35924220, 2022). "Previous genome-wide studies have identified an association between the rs2106261 single-nucleotide polymorphism (SNP) in the zinc finger homeobox 3 (ZFHX3) gene and an increased risk of atrial fibrillation (AF)." (PMID 34889223, 2021). "The previous genome-wide studies have shown that rs7193343 single-nucleotide polymorphism (SNP) in zinc finger homeobox 3 (ZFHX3) gene correlate with risk of atrial fibrillation (AF)." (PMID 26112950, 2015). "Though our signal for cholestanol is much farther downstream, SNPs in ZFHX3 have been linked to stroke and atrial fibrillation in prior GWAS." (PMID 24905834, 2014). "Previous genome-wide association studies (GWAS) showed association of variants near PITX2 and ZFHX3 with atrial fibrillation and stroke." (PMID 22776031, 2012). "ZFHX3, a zinc finger homeobox gene associated with atrial fibrillation and neurodevelopmental disorders, is expressed in vascular tissues and may regulate cytoskeletal gene expression and inflammatory pathways relevant to medial degeneration." (PMID 40981152, 2025). "Similarly, zinc finger homeobox 3, a zinc finger transcription factor involved in neuronal differentiation and atrial fibrillation susceptibility, has been identified in patients with intellectual disability and vascular anomalies." (PMID 40981152, 2025). "ZFHX3 were associated with atrial fibrillation and ischemic stroke." (PMID 38715006, 2024). "Strong links exist between genetic loci in PITX2 and ZFHX3 and cardioembolic stroke, which is mostly caused by atrial fibrillation (AF)." (PMID 40863347, 2025). "Genome-wide association studies (GWAS) significantly associated atrial fibrillation (AF) with two variants (rs7193343 and rs2106261) in the ZFHX3 gene that appear outside coding regions." (PMID 34884836, 2021). "The single nucleotide polymorphism (SNP) rs2106261 in the transcription factor gene ZFHX3 (16q22), a major regulator of inflammation, has been reported linking to atrial fibrillation (AF) by genome-wide association studies." (PMID 30180182, 2018). "Inflammation is known to be a strong predictor of atrial fibrillation recurrence after ablation, so we examined the association of the ZFHX3 SNP rs2106261 to inflammation marker expression and recurrence after AF ablation." (PMID 30180182, 2018). "Previous studies have suggested PITX2, KCNN3 and ZFHX3 as atrial fibrillation (AF) susceptibility genes." (PMID 28381281, 2017). "The gene zinc finger homeobox 3 (ZFHX3) encodes a transcription factor with cardiac expression and its genetic variants are associated with atrial fibrillation (AF)." (PMID 24983873, 2014). "Two genetic variants identified as contributing to the risk of atrial fibrillation (AF), in the genes PITX2 and ZFHX3, have also been shown to associate with cardioembolic stroke risk for which AF is an important risk factor." (PMID 21912753, 2011).
atrial fibrillation (continued). "ZFHX3 was identified as a crucial risk factor for atrial fibrillation, and SYNE2 contributed to atrial fibrillation." (PMID 35924220, 2022). "The zinc finger homeobox 3 (ZFHX3) gene encodes a transcription factor highly expressed in the heart and its genetic variants are associated with atrial fibrillation susceptibility." (PMID 27195777, 2016). "Genetic loci found to be associated with cardio-embolic ischemic stroke were already known risk loci for atrial fibrillation (PITX2 and ZFHX3), consistent with the fact that atrial fibrillation is by far the most common source of cardioembolic events." (PMID 27796860, 2016). "In our study we are focusing on a possible correlation between detection of atrial fibrillation by an implantable ECG recorder, and PITX2 and/or ZFHX3 gene mutations in cryptogenic stroke/TIA patients." (PMID 26631084, 2015). "In our study we are focusing on a possible correlation between detection of atrial fibrillation by implantable ECG loop, and PITX2 and/or ZFHX3 gene mutations in cryptogenic stroke/TIA patients." (PMID 26631084, 2015). "Interestingly, PITX2 and ZFHX3 are the principal genes associated with CES and atrial fibrillation, the most important risk factor for CES." (PMID 37686257, 2023). "Previous studies have consistently demonstrated the association between variants at 4q25 (PITX2) and 16q22 (ZFHX3) with atrial fibrillation both in patients with and without IS3,10, and additionally with cardioembolic stroke." (PMID 28939865, 2017). "ZFHX3 encodes ATBF1, a transcription factor involved in neuronal differentiation and survival that has also been previously implicated in Kawasaki disease, atrial fibrillation and ischemic stroke." (PMID 22916037, 2012). "It has been hypothesized that ZFHX3 may be a regulatory factor for the JAK/STAT signaling cascade and this cascade may be involved in atrial fibrillation susceptibility; however, further study is needed to clarify this relationship." (PMID 22384221, 2012). "Four SNPs near genes PITX2, ZFHX3, CAV1, and SYNPO2L are significantly linked with atrial fibrillation (AF), a significant stroke risk factor." (PMID 40863347, 2025). "Interindividual susceptibility likely varies by genetics: canonical atrial fibrillation loci (e.g., PITX2, ZFHX3) and variants in glycation pathway genes (e.g., AGER) may modify the association between acute–chronic glycemic mismatch and new-onset atrial fibrillation (NOAF)." (PMID 41040867, 2025). "Single nucleotide polymorphisms (SNPs) at chromosomes 4q25 (PITX2), 16q22 (ZFHX3), and 1q21 (KCNN3) have been shown to associate with atrial fibrillation (AF) in different genome-wide association studies (GWAS)." (PMID 28381281, 2017). "One genome-wide association studies loci with long-range chromatin conformation data identified a gene interaction network dominated by NKX2–5, TBX3, ZFHX3, and SYNPO2 L, which plays an important role in the pathogenesis of atrial fibrillation." (PMID 38765775, 2024). "PIAS2 is involved in the sumoylation of zinc finger homeobox 3 (ZFHX3), a transcription factor that is active in several pathological processes including atrial fibrillation and carcinogenesis, as well as in circadian regulation and development." (PMID 35887358, 2022).
prostate carcinoma (30 papers, 2008 to 2025). A carcinoma that arises from epithelial cells of the prostate gland. "The zinc finger homeobox protein 3 (ZFHX3) is a transcription factor often mutated in prostate cancer and it suppresses PI3K/AKT/mTOR signaling." (PMID 36768610, 2023). "While AR drives prostatic carcinogenesis, ZFHX3 is a tumour suppressor whose loss activates the PI3K/AKT signalling in advanced prostate cancer (PCa)." (PMID 34953044, 2022). "Many mutations in ZFHX3, a tumor suppressor gene frequently mutated in prostate cancer, were identified." (PMID 35347810, 2022). "Meanwhile, ZFHX3 has also been shown to modulate both normal development and carcinogenesis of the prostate, as ZFHX3 is frequently mutated in advanced human prostate cancer and loss of Zfhx3 in mouse prostates causes or promotes prostatic carcinogenesis." (PMID 34953044, 2022). "We noticed that ZFHX3 is a tumor suppressor in prostate cancer, as it is frequently mutated in advanced diseases, and its deletion induces or promotes prostatic carcinogenesis in mice." (PMID 33217982, 2020). "ZFHX3 is frequently mutated in metastatic or high-grade human prostate cancers, and many of the mutations are frameshifting and thus function inactivating." (PMID 30979864, 2019). "The exome of SC_9010 had a point mutation in ZFHX3/ATBF1, a tumor suppressor gene previously reported to be recurrently inactivated in prostate cancers." (PMID 27167109, 2016). "PPARGC1A and ZFHX3 are also reported to be associated with prostate cancer, which could partly explain their ability to predict relapse risk." (PMID 36103249, 2022). "ZFHX3 undergoes frequent loss‐of‐function mutation in advanced prostate cancer." (PMID 34953044, 2022). "In mammals, the zfh2 homolog ATBF1/ZFHX3 (AT-motif binding factor/zinc finger homeobox 3) is a demonstrated tumor suppressor, found frequently mutated in a large spectrum of human cancers (e.g. prostate cancer)." (PMID 31841513, 2019). "Therefore, MYC upregulation plays a causal role in the promotion of cell proliferation and colony formation by the loss of ZFHX3 in prostate cancer cells." (PMID 30979864, 2019). "Furthermore, CNV in miR-15a, CDH1 and ZFHX3 were associated with presence of incidental prostate cancer (p = 0.023, 0.003, 0.025, respectively)." (PMID 28915599, 2017). "In addition, CNV in miR-15a, CDH1 and ZFHX3 were associated with presence of incidental prostate cancer in the RC specimen (all p-values ≤ 0.025)." (PMID 28915599, 2017). "Previous experimentation performed in mice demonstrated that ZFHX3 acted as a tumor suppressor in prostate cancer, as its reduced expression disrupts the proper organization of the glands, affecting the layer of muscle between the stromal and epithelial cells." (PMID 37349324, 2023). "This distinction can prove important to the treatment of AA prostate cancer since functional ZFHX3 is necessary for effective ESR2 (aka ERß) agonist treatment." (PMID 36937425, 2023). "In cultured human prostate cancer cells, ZFHX3 is indispensable for oestrogen receptor beta (ERβ) to inhibit cell proliferation via MYC downregulation." (PMID 34953044, 2022). "We first surveyed the expression of ERα, ERβ, AR, and ZFHX3 in several prostate cancer cell lines by Western blotting." (PMID 30979864, 2019). "Findings in this study provide additional evidence for a tumor suppressor activity of ZFHX3 in AR-positive prostate cancer cells, as indicated by assays of SRB, colony formation in soft agar, and sphere formation in Matrigel." (PMID 30979864, 2019). "Higher levels of ZFHX3 and ERβ in human prostate cancer tissue samples correlated with better patient survival." (PMID 30979864, 2019).
prostate carcinoma (continued). "Considering that ERβ and ERα belong to the same protein family, sharing 97% similarity in their DNA-binding domains and 59% in their ligand-binding domains, it is possible that ZFHX3 also binds to ERβ in prostate cancer cells." (PMID 30979864, 2019). "Our finding of ZFHX3 as an indispensable factor for ERβ function in this study suggests that the status of ZFHX3 needs to be considered when restoring or enhancing ERβ activity via its agonists for the treatment of prostate cancer." (PMID 30979864, 2019). "For example, loss of ZFHX3 dramatically increased MYC expression in both C4-2B and LNCaP prostate cancer cells, and ZFHX3 clearly bound to the MYC promoter." (PMID 30979864, 2019). "Our data also suggest that intact ZFHX3 function is required for using ERβ-selective agonists to effectively treat prostate cancer." (PMID 30979864, 2019). "In this study, we examined the role of ERβ and ZFHX3 in and their interaction as a mechanism for the regulation of proliferation of AR-positive prostate cancer cells." (PMID 30979864, 2019). "Prostate cancer exhibits even more pronounced racial variations: Black men show higher frequencies of SPOP and ZFHX3 mutations but lower rates of TMPRSS2‐ERG fusions and PTEN deletions compared to White men, while Asian men demonstrate increased FOXA1 mutations and fewer PTEN alterations." (PMID 41187942, 2025). "ZFHX3 is frequently found to have numerous deletions in human prostate cancer (PCa)." (PMID 38871709, 2024). "Indeed, ZFHX3, a unreported susceptibility gene identified in the study, was regulated by androgen in prostate cancer cells, and the relationship between androgen/AR signaling and ZFHX3 modulates prostate cancer development and progression." (PMID 37612283, 2023). "A dynamic regulatory relationship between the androgen/AR signalling and ZFHX3, both of which modulate prostate cancer development and progression, could have therapeutic implications." (PMID 34953044, 2022). "To test whether androgen modulates ZFHX3 expression, we determined ZFHX3 expression in AR‐positive prostate cancer cell line LNCaP and its derivative C4‐2B under the treatment of the R1881 synthetic androgen." (PMID 34953044, 2022). "ZFHX3 inhibits the proliferation of prostate cancer cells by downregulating MYC gene expression." (PMID 33933102, 2021). "Direct binding of ZFHX3 to MYC promoter has also been detected in prostate cancer cells." (PMID 33217982, 2020). "Although these studies indicate a tumor-suppressive role of ZFHX3 in prostate cancer, it is unknown how ZFHX3 exerts such a suppressor function in prostate cancer." (PMID 30979864, 2019). "In this study, we tested whether and how ERβ and ZFHX3 coordinate to function in AR-positive prostate cancer cells." (PMID 30979864, 2019). "It is thus likely that ZFHX3 is also a regulator of androgen/AR signaling in prostate cancer." (PMID 30979864, 2019). "ZFHX3 has been established as a tumor suppressor in prostate cancer in our previous studies, as its gene undergoes frequent somatic mutations in advanced prostate cancer and its deletion in mouse prostates causes neoplastic lesions and promotes Pten deletion-induced tumorigenesis." (PMID 30979864, 2019). "Although ZFHX3 is clearly tumor suppressive in prostate cancer, how it exerts its tumor suppressor function was unknown." (PMID 30979864, 2019). "The presence of incidental prostate cancer was associated with CNV in miR-15a, CDH1 and ZFHX3." (PMID 28915599, 2017). "In summary, we found that in prostatic epithelial cells, androgen upregulates the transcription of ZFHX3 via the binding of AR to specific AREs in the ZFHX3 promoter, and the regulatory relationship between androgen/AR and ZFHX3 is valid in both mouse prostates and human prostate cancer specimens." (PMID 34953044, 2022). "Therefore, other unknown mechanisms are also responsible for ZFHX3’s tumor suppressor activity in prostate cancer cells." (PMID 30979864, 2019).